VDR (vitamin D receptor)
Diseases named in the same sentence as VDR in open-access papers (continued):
Sharing a sentence is not in itself a finding about the gene and the disease.
atopic dermatitis (12 papers, 2015 to 2026). "We analyzed publications that were focusing on levels of vitamin D and/or polymorphism analysis of vitamin D receptor gene in allergic asthma, rhinitis, and atopic dermatitis patients." (PMID 34343413, 2021). "As a result, individuals with specific VDR polymorphisms might exhibit variations in their susceptibility to various diseases, including atopic diseases like atopic dermatitis, allergic asthma, and allergic rhinitis." (PMID 38397449, 2024). "In addition, some authors showed a correlation between VDR gene polymorphisms and susceptibility to asthma and atopic dermatitis." (PMID 28891930, 2017). "Furthermore, several studies have demonstrated a significant association between VDR gene polymorphisms and asthma risk, or have indicated that rs2228570 could be associated with the risk of atopic dermatitis." (PMID 38397449, 2024). "In atopic dermatitis (AD), the expression of the vitamin D receptor (VDR) in keratinocytes and immune cells indicates that its activation contributes to the control of skin immunity and the maintenance of epidermal homeostasis." (PMID 41301826, 2025). "This case–control study investigated the relationship between VDR SNPs, vitamin D, and markers of atopy in Lithuanian adults with atopic diseases (atopic dermatitis and allergic asthma)." (PMID 38397449, 2024). "Association between the VDR and CYP24A1 polymorphisms and atopic dermatitis." (PMID 37632926, 2023). "Predicting new regulatory relationships through the identification of new potential VDR/Partner CEs may provide insight into the deep mechanisms of vitamin D involvement in the pathogenesis of atopic dermatitis, bronchial asthma, allergic rhinitis, and pulmonary infections." (PMID 41516283, 2025).
Cirrhosis (12 papers, 2013 to 2025). A chronic disorder of the liver in which liver tissue becomes scarred and is partially replaced by regenerative nodules and fibrotic tissue resulting in loss of liver function. "VDR-rs2228570 confers protection and is associated with increased survival in cirrhosis, as well as a better clinical profile for both conditions in the Brazilian cohort." (PMID 41561541, 2025). "Most studies showed an association between VDR gene polymorphisms and the development of cirrhosis by describing their effects on fibrosis." (PMID 37175993, 2023). "Haplotype association with cirrhosis severity was evaluated by the distribution of VDR haplotypes in the different CP stages." (PMID 30218108, 2018). "Genome-wide association studies (often termed GWAS) in PBC patients have revealed that VDR Bsm1 and Taq1 polymorphisms are associated with susceptibility to advanced fibrosis or cirrhosis." (PMID 29659559, 2018). "In conclusion, VDR-rs731236 and VDR-rs7975232 are associated with cirrhosis and HCC." (PMID 41561541, 2025). "Further research with larger cohorts is necessary to validate these associations and to explore the molecular mechanisms through which VDR polymorphisms influence the progression of cirrhosis and the development of HCC, as well as their impact on clinical outcomes and treatment response." (PMID 41561541, 2025). "This mutation results in a truncated protein; however, it is possible that the genomic function of VDR remains intact or that the presence of the polymorphic allele may confer protection against cirrhosis, as evidenced in this cohort." (PMID 41561541, 2025). "The VDR SNPs ApaI, BsmI, and TaqI were associated with the severity of cirrhosis." (PMID 37175993, 2023). "Other studies have also shown associations between VDR SNPs and cirrhosis." (PMID 35996514, 2022). "Firstly, polymorphisms of VDR have been associated with HCC in cirrhosis patients." (PMID 29659559, 2018). "Mutant homozygosity (CC) for VDR-rs731236 predominated in the cohort with HCC compared to isolated cirrhosis, consistent with findings in Chinese populations." (PMID 41561541, 2025). "Understanding the association of the molecular mechanisms involved in the progression of cirrhosis to HCC and the protective effects of VDR polymorphisms is essential for therapeutic advancements and improved prognosis for patients with this neoplasm." (PMID 41561541, 2025). "In conclusion, VDR-rs731236 and VDR-rs7975232 are associated with cirrhosis and HCC, with VDR-rs7975232 identified as independent predictors for isolated cirrhosis." (PMID 41561541, 2025). "We analysed the association of genetic polymorphisms of the VDR (VDR-rs2228570, VDR-rs731236 and VDR-rs7975232) in cirrhosis with or without HCC, considering clinical, biochemical profiles and survival." (PMID 41561541, 2025). "Furthermore, VDR-rs2228570 appears to confer protection and improve survival in cirrhosis, as well as enhance the clinical profile for cirrhosis and HCC within the Brazilian cohort." (PMID 41561541, 2025). "Thus, this study aimed to evaluate the association of genetic polymorphisms of the VDR (VDR-rs2228570, VDR-rs731236 and VDR-rs7975232) with clinical, biochemical profiles and survival outcomes in cirrhosis, with or without HCC patients." (PMID 41561541, 2025). "There are no data on the association between VDR gene polymorphisms and the risk of cirrhosis." (PMID 37175993, 2023). "However, a major link with CHC was identified in the coding region rs731236 (Taq1) indicating that the alteration of VDR protein may have a potential role in the development of cirrhosis." (PMID 35996514, 2022). "None of the VDR polymorphisms interacted significantly with the etiology of the disease, indicating that the effect of the polymorphisms is similar across all groups regarding cirrhosis’ etiology." (PMID 30218108, 2018).
Cirrhosis (continued). "We therefore tested the hypothesis of a link between VDR SNPs rs7970376 (G/A), rs11568820 (A/G), rs4516035 (T/C), rs2228570 (Fok1) (C/T), rs1544410 (Bsm-1) (G/A), rs731236 (Taq1) (T/C), and rs739837 (G/T) with cirrhosis and HCC in patients with chronic HCV infection." (PMID 35996514, 2022). "The HCC patients had a significantly higher cirrhosis rate than non-HCC patients (P < 0001), suggesting that the VDR polymorphisms at FokI locus may relate to HCC risk by enhancing the occurrence of liver cirrhosis." (PMID 23586065, 2013). "The negative correlation between the severity of fibrosis/cirrhosis and 25-hydroxy-vitamin D levels could also be due to the fact that vitamin D, through the activation (VDR) and Calcium-sensing receptor (CaSR), imparts portal hypotensive effect as evident from a study in a rat model." (PMID 36672644, 2023).
dengue (12 papers, 2012 to 2023). "A number of studies have looked for associations between polymorphisms in the VDR gene and dengue, as with studies investigating levels of vitamin D, there are inconsistencies within the literature." (PMID 37847693, 2023). "Few studies have shown the association of the vitamin D receptor (VDR) gene polymorphisms with susceptibility towards dengue virus infection." (PMID 36668950, 2023). "Since the effect of vitamin D is also dependent on single nucleotide polymorphisms in the VDR (vitamin D receptor) gene, the influence of vitamin D on dengue in the context of host genetics needs to be investigated." (PMID 36388314, 2022). "A few studies have explored the role of Vitamin D receptor gene polymorphism in dengue virus infection." (PMID 32375246, 2020). "Few studies have shown the association of the vitamin D receptor gene polymorphisms with susceptibility towards dengue virus infection." (PMID 32375246, 2020). "Another VDR gene polymorphism (rs 7975232) was screened in dengue positive cases and healthy controls." (PMID 32375246, 2020). "Since the effect of vitamin D is also dependent on single nucleotide polymorphisms in the VDR gene, the influence of vitamin D on dengue in the context of host genetics needs to be investigated." (PMID 22559908, 2012). "However, the role of vitamin D serum level in dengue pathogenesis and the association of VDR gene polymorphisms with the clinical severity of dengue infection has not been extensively studied in an Indian context." (PMID 32375246, 2020). "Interestingly, susceptibility to severe dengue disease has been associated with variations on in VDR and Fc receptors, that are crucial for antibody-dependent enhancement of infection during secondary encounters with the virus." (PMID 29020083, 2017). "Interestingly, several reports have already anticipated VDR genetic variants with clinical outcomes of dengue disease and oral vitamin D supplementation with disease recovery and moderate inflammation." (PMID 29020083, 2017). "It was shown in a small Vietnamese population where dengue is endemic that the low frequency of a dimorphic (T/t) “t” allele in the VDR gene was associated with dengue disease severity, suggesting a protective role of VDR activity against dengue disease progression." (PMID 27293435, 2016). "Interestingly, polymorphisms in the vitamin D receptor gene are linked with severe dengue disease outcomes." (PMID 26913918, 2016). "Guzman’s review summarises host factors that may reduce the risk of severe disease during a second dengue virus infection, which include race, second- or third-degree malnutrition, and polymorphisms in the Fcγ receptor and vitamin D receptor genes." (PMID 25209195, 2014). "Diverse single nucleotide polymorphisms (SNPs) in genes such as HLA-I, HLA-II, TNF-α, IL-10, TGF-β1, FcγRIIa, VDR, CD209 and OAS have been associated with symptomatic dengue or considered protective against the disease, in Asian and Latin American populations." (PMID 28241052, 2017). "Initially, it was reported that heterozygosity in the VDR gene was correlated with progression of dengue." (PMID 27293435, 2016). "Restriction Fragment Length Polymorphism was completed for the detection of vitamin D receptor (VDR) gene polymorphism; Results: Serum 25-hydroxy vitamin D3 (vitamin D) levels were found to be 1.6 times elevated in severe dengue cases as compared to healthy controls." (PMID 32375246, 2020). "RXRA forms heterodimers with VDR, previously identified as dengue protective in Vietnamese." (PMID 28241052, 2017). "It is proposed that NF-AT, SRF, and VDR may be involved in the regulation of immune response against dengue-mediated hypovolemic shock." (PMID 27038471, 2016). "In the present study it was observed that VDR gene and TLR 4 gene polymorphisms are associated with dengue virus infection in north Indian population but no such association was observed with TLR2 polymorphism." (PMID 34602778, 2021).
dengue (continued). "VDR and TLR4 but not TLR2gene polymorphisms were found to be associated with dengue susceptibility in Indian population." (PMID 34602778, 2021).
dental caries (12 papers, 2015 to 2024). The decay of a tooth, in which it becomes softened, discolored, and/or porous. "In our study, we evaluated factors affecting dental caries formation through surveys and biochemical measurements, investigating the relationship between vitamin D levels and VDR gene variants." (PMID 39857837, 2024). "The nuclear activation of the vitamin D receptor (VDR) gene is essential for the effectiveness of vitamin D. The main objective of this study is to determine the role of vitamin D levels and VDR gene variants in dental caries." (PMID 39857837, 2024). "Here, we investigated the relationship between this Fok1 RFLP in VDR locus and dental caries susceptibility, using a case-control study." (PMID 36034480, 2022). "The aim of this meta-analysis is to evaluate the association between these VDR polymorphisms (ApaI, FokI, TaqI, BsmI, and BglI) and susceptibility to dental caries in children." (PMID 33920959, 2021). "The present meta-analysis evaluated the association between VDR polymorphisms (ApaI (rs7975232), FokI (rs10735810), TaqI (rs731236), BsmI (rs1544410), FokI (rs2228570), and BglI (rs739837)) and the risk of dental caries in children." (PMID 33920959, 2021). "A number of studies on the associations of VDR gene polymorphisms, such as FokI, ApaI, BsmI, Cdx2, and TaqI, with the susceptibility to dental caries were published, and the TaqI (rs731236 T>C) polymorphism was the most studied variant." (PMID 33960841, 2021). "The role of VDR polymorphisms in modifying the effect of vitamin D supplementation on dental caries needs further exploration." (PMID 33920959, 2021). "More studies on larger sample sizes and different ethnicities will help to explore the influence of different VDR polymorphisms on the risk of dental caries." (PMID 33920959, 2021). "In this study it was investigated the relationship between polymorphisms in the vitamin D receptor gene and dental caries experience; participants over 12 years of age; laboratory assessment of 25(OH) D levels was not performed." (PMID 32895648, 2020). "This study investigated only the relationship between polymorphisms in the vitamin D receptor gene and dental caries susceptibility; laboratory assessment of 25(OH) D levels was not performed." (PMID 32895648, 2020). "Increased frequency of the CT and CC genotypes of the rs10735810 VDR gene polymorphism was associated with high risk of dental caries relative to the two other groups (χ2 = 6.715, P=0.036)." (PMID 31930121, 2019). "We conclude that these VDR polymorphisms cannot be used as markers for identification of Chinese children at increased risk of dental caries, when combined with environmental factors." (PMID 31930121, 2019). "The VDR gene contains more than 200 polymorphic sites, among which five single nucleotide polymorphisms related to dental caries have been studied: rs1544410, rs731236, rs7975232, rs10735810, and rs11568820." (PMID 31930121, 2019). "In a previous study, a VDR-FokI gene polymorphism was associated with dental caries in 12-year-old adolescents in China." (PMID 29849633, 2018). "Among the four examined VDR gene polymorphisms, the increased frequency of the CT and CC genotype of the Fok I VDR gene polymorphism was associated with dental caries in 12-year-old adolescent, compared with the controls (X2 = 17.813, p ≤ 0.001)." (PMID 29259981, 2017). "A total of 200 dental caries patients and 200 healthy controls aged 12 years were genotyped for VDR gene polymorphisms using the PCR-restriction fragment length polymorphism (PCR-RFLP) assay." (PMID 29259981, 2017). "The limitation of this study was that we only investigated the relationship between VDR polymorphisms and caries risk of children in Guangzhou, China; however, dental caries was caused by multiple genetic factors and environment." (PMID 28697775, 2017). "VDR protein mediated the biological function of Vitamin D, via interaction with the Vitamin D, which was associated with dental caries." (PMID 28697775, 2017).
dental caries (continued). "Vitamin D is likely to act through the vitamin D receptor and polymorphisms within this gene have been associated with dental caries." (PMID 26692013, 2015). "The aim of this study is to investigate the relationship between dental caries, which is still an important public health problem, and 25(OH)D levels, and VDR gene variants and to show whether vitamin D can be used as a potential agent against dental caries." (PMID 39857837, 2024). "Thus, this study assessed the relationship between single nucleotide polymorphism (rs2228570) in the vitamin D receptor gene and dental caries susceptibility." (PMID 36034480, 2022). "Hence, we considered it appropriate to evaluate the association of polymorphisms in VDR with biochemical levels of vitamin D in saliva and with dental caries." (PMID 36034480, 2022). "The VDR gene was found to impact the activity of a major metabolite of vitamin D, which participates in the formation of tooth enamel, which demonstrates its potential implication for dental caries risk." (PMID 33920959, 2021). "Out of the six VDR polymorphisms explored in this meta-analysis, an association was only observed between the FokI (rs10735810) polymorphism and the risk of dental caries, with the f allele and ff genotype demonstrating a protective role in the occurrence of dental caries." (PMID 33920959, 2021). "Given the role of VDR in enamel formation, we hypothesized a possible contribution of VDR gene polymorphisms to dental caries." (PMID 31930121, 2019). "Considering the role of the VDR gene in enamel formation, we hypothesized a possible contribution between VDR gene polymorphisms and dental caries." (PMID 29259981, 2017). "Concerning the incidence of dental caries, gene immune deficiency and inflammation alterations may contribute to host susceptibility and affect the course of caries, so we speculated that VDR gene polymorphisms might have relationship with dental caries." (PMID 29259981, 2017). "Based on the results of this study, the VDR gene variants rs7975232, rs10735810, rs1544410, rs11568820, and rs731236 are not suitable markers for identification of Chinese children with increased dental caries risk, when combined with environmental caries risk factors." (PMID 31930121, 2019). "In a meta-analysis that studied the correlation of all SNPs in VDR with dental caries, only Fok1 SNP showed a significant correlation with dental caries, which can be attributed to the location and cotranscription factors." (PMID 36034480, 2022). "We aimed to assess the association between the most common vitamin D receptor (VDR) polymorphisms (ApaI,FokI, TaqI, BsmI, and BglI) and the risk of dental caries in children." (PMID 33920959, 2021). "The VDR gene, which is a candidate gene related to dental caries, mediates the biological function of the major metabolite, Vit D, which is associated with enamel development." (PMID 31930121, 2019). "The VDR gene, identified as a candidate gene related to dental caries, mediated the biological function of the major metabolite of vitamin D, which was associated with enamel formation." (PMID 28697775, 2017). "Evidence here also sits in the context of recent work suggesting a potential role for vitamin D receptor in adult dental caries." (PMID 26692013, 2015). "In this study it was investigated only the relationship between polymorphisms in the vitamin D receptor gene and dental caries experience; laboratory assessment of 25(OH) D levels was not performed." (PMID 32895648, 2020). "In this study it was investigated the role of vitamin D receptor polymorphisms on dental caries; laboratory assessment of 25(OH) D levels was not performed." (PMID 32895648, 2020). "In a Czech study, the VDR TaqI gene variant could not be used as a marker for identification of children with increased dental caries risk either." (PMID 29849633, 2018).